IRAK1BP1 (interleukin 1 receptor associated kinase 1 binding protein 1)
Description:
Component of the IRAK1-dependent TNFRSF1A signaling pathway that leads to NF-kappa-B activation and is required for cell survival. Acts by enhancing RELA transcriptional activity (By similarity).
Synonyms: AIP70; SIMPL
Tractability: PROTAC: ubiquitination databases record sites on it.
Gene: Protein-coding gene on chromosome 6 (78,867,551 to 78,946,440, forward strand). Ensembl gene ENSG00000146243.
Subcellular location: Cytoplasm; Nucleus
Subcellular location (Human Protein Atlas): Vesicles
Gene Ontology:
Molecular function: protein binding; signaling adaptor activity
Biological process: positive regulation of canonical NF-kappaB signal transduction; immune response
Cellular component: cytoplasm; nucleus
Genetic constraint (gnomAD): Loss-of-function variants: 20 observed, 23.14 expected, observed/expected ratio (o/e) 0.86, 90% interval 0.61 to 1.26. The upper end of that interval is the gene's LOEUF score, 1.26, which puts it in group 5 of 6, group 1 being the genes least tolerant of losing a copy. Missense variants: 290 observed, 288.61 expected, observed/expected ratio (o/e) 1, 90% interval 0.91 to 1.11. Synonymous variants: 115 observed, 109.37 expected, observed/expected ratio (o/e) 1.05, 90% interval 0.9 to 1.23.
Homologues: Orthologues: macaque IRAK1BP1 (96% identical), chimpanzee IRAK1BP1 (95% identical), dog IRAK1BP1 (90% identical), pig IRAK1BP1 (89% identical), rabbit IRAK1BP1 (87% identical), mouse Irak1bp1 (82% identical), rat Irak1bp1 (79% identical), tropical clawed frog irak1bp1 (51% identical), guinea pig Irak1bp1 (48% identical), zebrafish irak1bp1 (38% identical).
Diseases named in the same sentence as IRAK1BP1 in open-access papers:
IRAK1BP1 is named in the same sentence as 12 diseases in open-access papers, as found by Europe PMC text mining. Sharing a sentence is not in itself a finding about the gene and the disease. The quoted sentences say what the papers report.
lung adenocarcinoma (2 papers, 2023). A carcinoma that arises from the lung and is characterized by the presence of malignant glandular epithelial cells. "The loss of IRAK1BP1 is associated with poor prognosis in patients with lung adenocarcinoma." (PMID 37941550, 2023).
periodontitis (2 papers, 2020 to 2022). An acute or chronic inflammatory process that affects the tissues that surround and support the teeth. "Hypermethylation was found in TLR regulators genes: MAP3K7, MYD88, IL6R, RIPK2, FADD, IRAK1BP1, and PPARA in early stages of periodontitis, while advanced stages presented hypomethylation of these genes." (PMID 36233348, 2022).
dermatitis (1 paper, 2017). An inflammatory process affecting the skin. "It was of interest to evaluate IMQ dermatitis in MOLF mice, since previous studies have identified MOLF genetic variants impacting Toll-like receptor (TLR) signaling, including alleles associated with Tlr5, Irak1bp1, Irak2, Irak2c, and Cyld." (PMID 28279190, 2017).
lung carcinoma (1 paper, 2023). "Our findings suggest that elevated IRAK1BP1 is associated with suppressed oncogenic signatures in both lung cancer cell lines and patient data, further showing promise for IRAK1BP1 as a predictor of lung cancer prognosis." (PMID 36994215, 2023). "The differential expression of IRAK1BP1 in various cancer types warrants further survival analysis in cancers other than lung cancer." (PMID 36994215, 2023). "Further validating the predictive power of IRAK1BP1, our GSEA analysis of high-IRAK1BP1 expressers using RNA-seq data from lung cancer cell lines in the cancer cell line encyclopedia (CCLE) database showed remarkable similarity to the GSEA results in patient data." (PMID 36994215, 2023).
tumor (3 papers, 2015 to 2023). "Our analyses showed that IRAK1BP1 is not only one of the 9 LUAD-specific DEGs that are common to the 6 datasets that were analyzed, but also possesses predictive potential, as the reduced expression of IRAK1BP1 alone in tumor samples predicts poor survival." (PMID 36994215, 2023). "In the context of cancer, chronic inflammation is often associated with tumor development; therefore it would be interesting to test if the reduced expression of IRAK1BP1 in tumor cells leads to elevated inflammatory signals and contributes to cancer progression." (PMID 36994215, 2023). "Our analysis suggests that IRAK1BP1 is an independent prognostic factor of LUAD that robustly predicts LUAD tumor progression, which may be valuable for future development of personalized treatments." (PMID 36994215, 2023). "In addition, loss of IRAK1BP1 correlated with the group of LUAD patients with worse survival; and gene-set enrichment analysis using tumor and cell line data implicated that high IRAK1BP1 expression was associated with suppression of oncogenic pathways." (PMID 36994215, 2023). "To find out how IRAK1BP1 may assist in tumor formation and progression, we performed gene-set enrichment analysis (GSEA) as well as gene ontology analysis for LUAD samples in the high-IRAK1BP1 group." (PMID 36994215, 2023).
cancer (1 paper, 2023). A tumor composed of atypical neoplastic, often pleomorphic cells that invade other tissues. "The association of IRAK1BP1 with cancer is a novel discovery, while the function of IRAK1BP1 in cancer remains to be explored." (PMID 36994215, 2023). "Interestingly, the differential expression of IRAK1BP1 is also observed in other cancer types: we assessed IRAK1BP1 expression for all cancer types with available data." (PMID 36994215, 2023). "While studies have elucidated the anti-inflammatory function of IRAK1BP1, the association between IRAK1BP1 and cancer has not been reported and its role in cancer is unknown." (PMID 36994215, 2023).
IRAK1BP1 also shares sentences with these, for which no sentence is quoted: breast carcinoma (1 paper); colon adenocarcinoma (1); diabetes (1); kidney cancer (1); prediabetes (1); prostate adenocarcinoma (1).